PECAM1 (platelet and endothelial cell adhesion molecule 1)
Diseases named in the same sentence as PECAM1 in open-access papers (continued):
Sharing a sentence is not in itself a finding about the gene and the disease.
hematoma (11 papers, 2013 to 2026). A hematoma is a collection of blood from a vascular structure into an extravascular space. "On day 1 after ICH, the expression of VCAM‐1, ICAM‐1, and PECAM‐1 were significantly up regulated in the peri‐hematoma region when compared to the sham group." (PMID 38044319, 2024).
malaria (11 papers, 2008 to 2024). Malaria is a serious and sometimes fatal disease caused by a parasite that commonly infects a certain type of mosquito which feeds on humans. "Similarly, PF3D7_1300300/PF13_0003, PF3D7_0425800/PFD1235w contain DC5 which was associated with severe malaria in one study and also with parasite binding to the human receptor PECAM1." (PMID 25479608, 2014). "In contrast, a decreased expression of PECAM-1 was observed in patients experiencing malaria when compared to the same patients after treatment." (PMID 25233271, 2014). "In malaria pathway, PECAM1 was expressed highly to enhance cell adhesion." (PMID 32632500, 2020). "BOEC’s derived from cryopreserved small-volume PBMC samples from Ghanaian malaria patients (n = 8) all expressed EPCR, ICAM-1, thrombomodulin and PECAM-1." (PMID 30300360, 2018). "For example, the KEGG term “Malaria” is enriched in the UP genes in RA due to genes such as CR1, GYPA, ICAM1, PECAM1, and TLR4." (PMID 28491277, 2016). "Importantly, and of physiological relevance to adhesion and malaria pathogenesis, this parasite sub-line was found to bind both CD31/PECAM1 and CD54/ICAM1 and to adhere twice as efficiently to human endothelial cells, compared to infected cells having only one PfEMP1 variant on the surface." (PMID 20824088, 2010). "The involvement of Integrins αV and PECAM-1 in CM has been reported; however, the significance of ICAM-3 and N-cadherin in malaria disease has not been established yet." (PMID 37048057, 2023). "The aim of this study was to investigate the association of SNPs of three adhesion molecule genes, ICAM1, PECAM1 and CD36, with severity of falciparum malaria in a malaria-endemic and a non-endemic region of India." (PMID 19055786, 2008).
osteosarcoma (11 papers, 2010 to 2025). A usually aggressive malignant bone-forming mesenchymal neoplasm, predominantly affecting adolescents and young adults. "The vascularendothelial cell population in the osteosarcoma lesion tissues exhibiteda PECAM1­(+), CDH5­(+) phenotype, whereas the macrophage populationwas predominantly of the M2 type, expressing CD163­(+) and MRC1­(+),consistent with the characteristics of the tumor immune microenvironment." (PMID 40834268, 2025).
hemangioendothelioma (10 papers, 2010 to 2025). A vascular proliferation characterized by the presence of prominent endothelial cells and the formation of vascular channels. "In the present study, the use of 2′-O-methyl-modified siRNA-cluster of differentiation 31 (siRNACD31), with cationic liposome RNA interference (RNAi)-mate as a carrier, effectively silenced the platelet endothelial cell molecule 1 (PECAM-1) gene of murine hemangioendothelioma cells in vitro." (PMID 24959215, 2014).
psoriasis (10 papers, 2013 to 2025). An autoimmune condition characterized by red, well-delineated plaques with silvery scales that are usually on the extensor surfaces and scalp. "We found one crossover locus of IL13 for psoriasis, two crossover loci BLK and ITGAM/ITGAX genes for SLE and four crossover loci near TFPI, CYP2A1, PECAM1, and CXCL12 for CAD data set." (PMID 32779262, 2020). "Based on the IPA analysis BmA pre-exposure before LPS E. coli re-stimulation affected several pathways like granulocyte and agranulocyte adhesion and diapedesis (PPBP/CXCL7, PECAM1, CCL20, CXCL5, CXCL6, MMP9), IL-17 in psoriasis, arthritis and signaling in airway cells (CCL20, CXCL5, CXCL6)." (PMID 30796272, 2019).
ulcer (10 papers, 2012 to 2025). "They found that factors such as disease perception, ulcer duration, and biochemical markers (e.g., IL-6, microRNA-146a-5p, PECAM-1, and angiopoietin-2) had substantial predictive value for healing outcomes." (PMID 40620799, 2025). "Compared to the ulcer group, the Cls and Omp groups produced significant increases in gastric PECAM-1 immunoexpression." (PMID 38884677, 2024). "Pioglitazone, a PPAR-γ agonist, was very effective in speeding up the healing of ulcers by stimulating PECAM-1-induced angiogenesis." (PMID 38884677, 2024). "Our results showed that the expression of pErk-1 and PECAM-1 were increased in rats with ethanol-induced ulcers that were pretreated with Cls." (PMID 38884677, 2024). "In this study, we proposed that the ability of Cls to block ROS, IL-1β, IL-6, TNF-α, NF-κB, and caspase-3 as well as increase pErk-1, NO, PECAM-1, and PPAR-γ levels partly explains why it protects the stomach against ethanol-induced ulcer." (PMID 38884677, 2024). "Cls stimulated ulcer healing and inhibited apoptosis by activating pErk-1 and PPAR-γ which led to increased PECAM-1 expression and NO level and decreased caspase-3 expression." (PMID 38884677, 2024).
Cirrhosis (9 papers, 2014 to 2023). A chronic disorder of the liver in which liver tissue becomes scarred and is partially replaced by regenerative nodules and fibrotic tissue resulting in loss of liver function. "However, in the case of cirrhosis weak immunoreactivity for PECAM-1 observed on sinusoidal epithelial cells (SEC) and endothelial cells of vessels in portal tracts in normal liver increases significantly." (PMID 29699354, 2014).
multiple sclerosis (9 papers, 2006 to 2024). A progressive autoimmune disorder affecting the central nervous system resulting in demyelination. "For instance, during progression of experimental autoimmune encephalomyelitis (a model for multiple sclerosis), mononuclear cell extravasation and infiltration of the brain in PECAM-1-deficient mice are considerably enhanced." (PMID 23773279, 2013). "Elevated serum PECAM-1—contrasting a local reduction—has also been observed in other diseases with a compromised vascular barrier, such as multiple sclerosis." (PMID 38157091, 2023). "Other genes that were downregulated include Aldh1a, known to be involved in detoxification, and Pecam1, involved in the promotion of vascular repair mechanisms and blood–brain barrier integrity after multiple sclerosis (MS)-like insults and either directly or indirectly involved in myelination." (PMID 37240038, 2023).
unstable angina (9 papers, 2014 to 2024). "The aim of this case-control association study was to evaluate the associations between the occurrence of acute coronary syndromes in the form of unstable angina and SNPs within the PECAM1, COL4A2, PHACTR1 and LMOD1 genes." (PMID 35054067, 2022). "The aim of this study was to evaluate the association between the PECAM1 (rs1867624), COL4A2 (rs4773144), PHACTR1 (rs9349379) and LMOD1 (rs2820315) gene polymorphisms and the risk of unstable angina." (PMID 35054067, 2022).
viral infection (9 papers, 2011 to 2024). "The endothelial genes PECAM1/CD31 and ENG were both enriched in regions of viral infection, further supporting our assertion of viral infection at the capillary bed." (PMID 36968839, 2023). "MIR2 function may play an important role in immune evasion of the virus and resultant persistent viral infection by MIR2-mediated down-regulation of MHC-I and platelet endothelial cell adhesion molecule 1 (PECAM-1)." (PMID 22191032, 2011).
acute coronary syndrome (8 papers, 2014 to 2022). Signs and symptoms related to acute ischemia of the myocardium secondary to coronary artery disease. "PECAM-1 has been suggested as a sensitive marker providing early diagnostic aid in acute coronary syndromes." (PMID 31936828, 2020).
Arthritis (8 papers, 2011 to 2025). Inflammation of a joint. "Among them, PECAM1 and PTPRJ were shown to play a role in the protection against arthritis and exert anti-fibrotic effects, respectively." (PMID 37205098, 2023).
endometrial cancer (8 papers, 2009 to 2025). Primary or metastatic malignant neoplasm involving the endometrium (mucous membrane that lines the endometrial cavity). "Furthermore, a comprehensive assessment of PECAM1 across various cancer types revealed that PECAM1 was consistently expressed at low levels compared to normal tissues, including bladder, breast, esophageal, colon, cervical, renal cell, pancreatic, rectal, and endometrial cancers." (PMID 40361912, 2025).
epilepsy (8 papers, 2018 to 2025). A brain disorder characterized by episodes of abnormally increased neuronal discharge resulting in transient episodes of sensory or motor neurological dysfunction, or psychic dysfunction. "PECAM1 gene encodes a transmembrane protein in endothelial cells and platelets, which is essential for angiogenesis, inflammation, and intercellular interactions, potentially influencing the blood–brain barrier and neurovascular units in epilepsy." (PMID 40520613, 2025). "Thus, it is possible to speculate that the increased early PECAM-1 expression observed in the hippocampal CA3 region after the KA injection in the present study was related to the epilepsy-induced neuronal death." (PMID 30258402, 2018). "According to the ROC curves, the expression level of key genes including CTSD, CREG1, PECAM1, ZNF101, RRM2B, MARCKSL1, and MAP2K4 demonstrated a certain accuracy in classifying epilepsy and control groups (0.7 < AUC < 0.9)." (PMID 40520613, 2025). "The ROC curves revealed that the expression levels of key genes NCAM1, CPVL, PECAM1, and TNC had high accuracy in classifying epilepsy and control groups (AUC >0.9)." (PMID 40520613, 2025).
experimental autoimmune encephalomyelitis (8 papers, 2012 to 2022). An autoimmune demyelinating disease of the central nervous system that is produced experimentally in animals by the injection of homogenized brain or spinal cord in Freund's adjuvant. "In several autoimmune murine models, including experimental autoimmune encephalomyelitis, PECAM-1-deficiency leads to a more severe disease course." (PMID 35683597, 2022). "Conversely, GSK3β activation has been implicated in causing a “leakier” BBB in mice deficient of platelet endothelial cell adhesion molecule (PECAM-1), developing a more severe experimental autoimmune encephalomyelitis." (PMID 23418486, 2013).
thrombosis (8 papers, 2018 to 2023). "In our previous study using the laser-induced thrombosis model, we showed that the increase in the antiplatelet effect correlated with the increase in the PECAM-1/thrombus ratio in healthy mice." (PMID 34502520, 2021). "In LPS-treated mice, the PECAM-1/thrombus ratio decreased as the dose of ASA increased in both thrombosis models, but the direction of change in the thrombus area was inconsistent." (PMID 34502520, 2021). "In this study, we used a lipopolysaccharide (LPS)-induced mouse model of inflammation to evaluate platelet activity using the PECAM-1/thrombus ratio in two thrombosis models: a flow chamber model and laser-induced thrombosis model." (PMID 34502520, 2021). "At the site of venous thrombosis, a soluble subform of PECAM-1 (sPECAM-1) is generated by proteolytic cleavage at the cell surface with consecutive sPECAM-1 plasma level elevation." (PMID 32215782, 2020).
aneurysm (7 papers, 2016 to 2024). Bulging or ballooning in an area of an artery secondary to arterial wall weakening. "Staining the retina with an anti-PECAM1 antibody to highlight the retinal vasculature revealed aneurysms in all eGFP control-injected eyes." (PMID 34182803, 2021).
diabetic nephropathy (7 papers, 2005 to 2025). "In the human kidney samples with diabetic nephropathy, there were PECAM-1-positive glomerular endothelial cells reacted with both anti-PECAM-1 and anti-TLR2, and cells only immunostained with anti-TLR2." (PMID 24835775, 2014).
lupus (7 papers, 2017 to 2025). "Specifically, ligand–receptor pairs such as Thy1-(Itgam+Itgb2), Mif-(Cd74+Cxcr4), Tgfb1-(Tgfbr1+Tgfbr2), and Pecam1-Pecam1 showed higher mean expression levels in lupus mice than in DHA-treated mice." (PMID 40728997, 2025). "TLR7/8 activation impaired gut integrity in lupus-prone TC mice but not in congenic controls based on the FITC-dextran assay, and it lowered the expression of Claudin-1 between gut epithelial cells and PECAM1 between blood/lymphatic endothelial cells." (PMID 37483626, 2023).
meningioma (7 papers, 2016 to 2024). A generally slow growing tumor attached to the dura mater. "AQP1, FRZB, PDGFRL, and PECAM1 were consistently underexpressed in meningioma samples; MEDAG, MYC, PAMR1, PDPN and PERP were consistently overexpressed in nearly every meningioma sample by both measurements." (PMID 29073243, 2017). "Five genes that were down-regulated in the meningiomas compared to the control tissue included AQP1 (aquaporin 1), FRZB (Frizzled b), PECAM1 (platelet and endothelial cell adhesion molecule 1), PDGFRL (platelet-derived growth factor receptor-like), and FBLN2 (fibulin 2)." (PMID 29073243, 2017).
Alzheimer disease (6 papers, 2016 to 2026). A progressive, neurodegenerative disease characterized by loss of function and death of nerve cells in several areas of the brain leading to loss of cognitive function such as memory and language. "Current understanding points to a reduced endothelial expression of PECAM-1 in Alzheimer’s disease compared to healthy individuals and decreased expression in arterial beds relative to venous and capillary." (PMID 37333410, 2023). "PECAM1 was also shown to be involved in the pathogenesis of Alzheimer’s disease via promoting neuroinflammation." (PMID 36568118, 2022). "With their innate physiological roles as well as being direct interacting partners (guilt-by-association) to already known AD genes (JAK2 and PECAM1) increases the chances of the two genes (CSF1R and GAB1) as novel candidate genes for Alzheimer’s disease." (PMID 26784894, 2016).
gastric ulcer (6 papers, 2014 to 2024). An ulcerated lesion in the mucosal surface of the stomach. "Both HCl/ethanol- and indomethacin-induced gastric ulcers showed increased TNF-α, IL-6, Evans blue permeation, and PECAM-1, and decreased COX-2, PGE2, occludin, and LPA5 receptor expression levels." (PMID 38069044, 2023).
liver disease (6 papers, 2014 to 2021). "In this paper, we analyzed the clinical significance of serum angiogenic markers VEGF, Ang-1, Ang-2, angiopoietin receptor Tie1/2, HGF, and PECAM-1 in 62 patients with liver disease, out of which 33 were diagnosed with HCC and 29 with liver cirrhosis without signs of neoplasia." (PMID 35008171, 2021). "Similarly, CXCL1 and CXCL9 have chemotactic activities and roles in angiogenesis, inflammation and tumor genesis, CXCL12 is related to the HCC metastatic network by recruiting endothelial cell tumor progenitors, and PECAM-1 reflects the liver disease progression." (PMID 26226632, 2015). "Therefore, blockade of PECAM-1 and decreased blood vessel formation could lead to increased portal hypertension." (PMID 24734240, 2014).
pterygium (6 papers, 2009 to 2023). A wedge-shaped fibrovascular lesion arising from the bulbar conjunctiva and extending to the cornea. "Consistent with our results, immunostaining of PECAM1 revealed much richer vascularization in pterygium." (PMID 33790949, 2021). "Compared with the conjunctiva, several key factors related to angiogenesis, such as PECAM1, CD34, VWF, and ENG, were highly expressed in the pterygium." (PMID 33790949, 2021). "Our results supported the dysregulation of 19 of these genes in pterygium, for example, TRAP100, MIP-4, RBP-1, MAP-17 and PECAM1." (PMID 19272163, 2009).
renal carcinoma (6 papers, 2014 to 2025). A carcinoma arising from the epithelium of the renal parenchyma or the renal pelvis. "This suggests that PECAM1/CD31 and CCND1 could be used as indicators for the early diagnosis of renal cancer." (PMID 31850854, 2019). "Finally, to investigate early events in renal cancer, we screened for the hub genes CCND1 and PECAM1/CD31." (PMID 31850854, 2019).
squamous cell carcinoma (6 papers, 2020 to 2025). A carcinoma arising from squamous epithelial cells. "Furthermore, a survival plot showed that the high expression of some hub genes (FOXO3, CCR5, PECAM1, ESR1, and SMAD2) was associated with high risk of death in patients with esophageal carcinoma and other squamous cell carcinomas." (PMID 33747034, 2021).
adenomyosis (5 papers, 2014 to 2026). The growth of endometrial tissue inside the muscular wall of the uterine corpus. "In order to increase the credibility of our results, additional leiomyoma (n = 3) and adenomyosis (n = 3) samples were used to confirm EPCAM and PECAM1 colocalization and VM formation." (PMID 33685511, 2021). "Through single-cell RNA sequencing of adenomyosis tissues, we identified epithelial-endothelial transition (EET) as a key pathological mechanism and discovered transitional cells co-expressing epithelial (EPCAM) and endothelial (PECAM1) markers." (PMID 41861114, 2026).
cognitive deficits (5 papers, 2017 to 2024). "Chronic ethanol exposure induces oxidative stress and neuroinflammation, in part mediated by endothelial PECAM-1, which may contribute to blood-brain barrier damage, and reduced oligodendrogenesis and demyelination and cognitive deficits." (PMID 29035306, 2017). "Moreover, PECAM-1 could be considered as a potential therapeutic target for protecting the CNS from the cytotoxicity exerted by the immune cells and preventing the sustained cognitive impairment observed in conjunction with brain atrophy, even later than 6 months after surgery." (PMID 31574089, 2019).
cutaneous melanoma (5 papers, 2014 to 2025). A primary melanoma arising from atypical melanocytes in the skin. "In addition, the spatial transcription data on SpatialDB showed that RAB5B spatially overlapped with endothelial cell markers PECAM1 and VWF in BCC cancer tissues and M2 macrophage markers CD68 and CD163 in skin melanoma tissues." (PMID 40842984, 2025).
depression (5 papers, 2020 to 2024). "In the current study, we demonstrated that two biomarkers, ICAM-1 and PECAM-1, were significantly higher in the serum of patients associated with cognitive dysfunction, depression, vestibulocerebellar ataxia, and in the group of patients following chemotherapy." (PMID 35366289, 2022). "Our study found a statistically significant increase in ICAM-1, PECAM-1 in the blood of women with depression." (PMID 35366289, 2022). "Increased serum levels of soluble ICAM-1 and PECAM-1 are observed in a number of neuropsychiatric disorders (i.e., depression, bipolar disorder, dementia, and progressive vascular cognitive disorders)." (PMID 35366289, 2022). "In addition, changes in serum PECAM1 levels contribute to the occurrence and development of autism and depression." (PMID 33328875, 2020). "Our CytoHubba analysis identified six hub genes (PECAM1, TLR2, PTGS2, LRRK2, HCK, and IL18), all significantly upregulated in both depression and hypovitaminosis D, with PTGS2 having the highest inference score and reference count." (PMID 38256187, 2024).
Hepatitis (5 papers, 2018 to 2024). Inflammation of the liver. "Expression of VCAM-1 is significantly enhanced in mice that develop hepatitis after ConA injection, while the role of PECAM-1 in leukocyte transmigration during the liver inflammation is well known." (PMID 33809904, 2021).
kidney tumor (5 papers, 2012 to 2023). "The mRNA expression of CCND1 and PECAM1/CD31 were compared between kidney tumor samples and adjacent normal tissues respectively based on RNA-sequence data from TCGA database." (PMID 31850854, 2019).